BMP2 (bone morphogenetic protein 2)
Diseases named in the same sentence as BMP2 in open-access papers (continued):
Sharing a sentence is not in itself a finding about the gene and the disease.
tumor (continued). "The results indicated that BMP2, which induces the expansion of MDSCs in bone marrows, could enhance proliferation and the tumor sphere formation of HCC cells." (PMID 32195173, 2020). "In summary, the roles that BMP2 plays in tumor progression may be affected by the types of cancer and the microenvironment, which needed future research." (PMID 32195173, 2020). "Given the reported upregulation of BMP2 in NPC tumour samples and our current observations on elevated BMP2 expression in C666-1 cells, we chose to examine the basal levels of BMP2 expression in a panel of EBNA1-expressing cell lines as compared with cells latently infected with EBV." (PMID 32708289, 2020). "In addition, the knockdown of TrkB restored the tumor-inhibitory effect of BMP-2 via the activation of SMAD1." (PMID 32731498, 2020). "In addition to this effect on epithelial stem cells we revealed an impact of BPA on the tumor microenvironment through the induction of the synthesis of high levels of BMP2 by normal fibroblasts and stromal cells." (PMID 31547326, 2019). "SPP2 has been shown to bind to BMP-2 and inhibit tumor growth through the blockage of BMP-2." (PMID 31849319, 2019). "OASL, EGR1, and BMP2 were significantly downregulated in tumor in GSE13861." (PMID 30134903, 2018). "BMP-2 may contribute to the invasiveness of tumour cells via induction of the extracellular matrix glycoprotein Tenascin-W in the tumour-surrounding stroma." (PMID 28733469, 2017). "This may reflect why MDA-MB-231, an ER-negative tumour cell line, responds to recombinant human BMP-2 with a more significantly reduced proliferation, in comparison with the ER positive MCF-7 cells." (PMID 28733469, 2017). "According to the correlation analysis between BMP2 expression level and clinical-pathological features of NPCs, BMP2 overexpression was significantly positively correlated with tumor size, lymph node metastases, distant metastasis and clinical stage in NPC patients." (PMID 28455969, 2017). "However, there is concern regarding the effect of locally applied BMP-2 on tumor recurrence and metastasis." (PMID 28264040, 2017). "BMP-2 upregulation of target gene ID-1 (which activates pathways involved in tumour progression) may contribute to this effect." (PMID 28733469, 2017). "BMP-2 expression is significantly higher in the ER-negative tumours." (PMID 28733469, 2017). "Alternatively, this may be due to the development of a CA-MSC-like expression profile (with increasing levels of BMP2 and 4) in normal adipose-derived MSCs after long periods of tumor stimulation." (PMID 26755648, 2016). "The effect of BMP-2 on tumor microvessel density (MVD) was examined." (PMID 27886213, 2016). "BMP-2 has been reported to either stimulate or inhibit tumor growth, depending on cancer type." (PMID 27293448, 2016). "In a follow-up study, the authors evaluated whether BMP-2 can be used to block the tumor-initiating ability of human renal ALDH+ CSCs in vitro and induce bone formation in vivo." (PMID 27293448, 2016). "However, the inhibitory effect of BMP-2 in tumors is controversial and some studies have shown that it stimulates tumor growth, indicating that the action of BMP-2 on tumor growth probably depends on the cancer type." (PMID 27891093, 2016). "Moreover, phosphoprotein Spp24 secreted by BMP binding protein diminished BMP-2-initated tumor growth and thus resulted in significant apoptosis of cancer cells, which would be developed into a new therapeutic agent for clinical applications." (PMID 27661009, 2016). "In particular, involvement of bone morphogenetic protein 2 (BMP-2) produced by tumor cells in both primary and metastatic sites as well as the expression of a BMP type 1 receptor called BMP-Ib in the metastatic sites, were all reported to play a role in the osseous formation." (PMID 26264044, 2015).
tumor (continued). "SPP24 appears to reduce the growth of tumour cells by binding to both BMP-2 and TGF-β in vitro, but whether plasma SPP24 is upregulated during tumourigenesis in vivo is not currently known." (PMID 25652121, 2015). "The results showed that AdLMP-1 increased the expression of both Runx2 and BMP-2 in OS cells, which suggested that the osteogenetic roles of Runx2 and BMP-2 may be involved in LMP-1-mediated tumor suppression." (PMID 24762763, 2014). "Additionally, tumor growth was promoted in nude mice that were injected with A549 cells that were transfected with recombinant BMP-2." (PMID 24946687, 2014). "BMP-2 enhances tumor angiogenesis and stimulates tumor invasion." (PMID 23593444, 2013). "We concluded that we can efficiently express BMP-2 through a bacterial vector and that the resulting bacterial clones would allow testing of whether production of the tumour suppressive cytokine in this bacterial context has anticancer activity." (PMID 22315590, 2012). "Together, these data indicate that BMP-2 acts as a powerful tumor suppressor in the columnar intestine and thus that application of exogenous BMP-2 may be useful in combating cancer cells." (PMID 22315590, 2012). "Others have also shown that BMP-2 can induce tumor growth under certain conditions." (PMID 23049692, 2012). "It is likely that within the tumor microenvironment, mammary cells that express BMP2 could use any available source of phosphate to produce mammary microcalcifications." (PMID 22911843, 2012). "However, BMP2 has been shown in some settings to enhance tumor growth in vivo due to activation of Smad-1/5." (PMID 22870311, 2012). "Importantly, these effects were downregulated both by hypoxia and by HIF-1α, whose stabilization obtained with either CoCl2 or by using proteasome inhibitor (Z-LLF) was preventing BMP2 induced Akt/mTOR activation, especially in tumor cells." (PMID 19587783, 2009). "The expression of BMP-2 in tumor tissues from patients was inversely correlated with survival." (PMID 19366455, 2009). "We found that SDH activity was increased following BMP2 treatment, suggesting that pro-differentiating agents, such as BMPs, may promote a metabolic shift toward oxidative phosphorylation also in tumor cells." (PMID 19587783, 2009). "Notably, in normal SVZ cells SDH activation was not changed following BMP2 treatment, this indicating differences in metabolic response to BMP2 treatment between normal and tumor cells." (PMID 19587783, 2009). "Recent research demonstrates that tumor-intrinsic deficiency of SET domain containing 2, a histone lysine methyltransferase, drives transcriptional reprogramming through aberrant H3K27 acetylation deposition and promotes bone morphogenetic protein 2(BMP2) signaling pathway activation." (PMID 40861469, 2025). "Thus, BMP2 can be produced autonomously by tumor cells in response to specific stresses." (PMID 39373720, 2024). "Additionally, tumor cells expressed Bmp2 and low levels of Gdf11, Bmp4, and Tgfb1." (PMID 38304252, 2023). "Furthermore, BMP-2 was strongly expressed by tumor cells and weakly expressed by stromal cells, suggesting that tumor cells strongly secrete BMP-2, which may have transformed fibroblasts and pluripotent stem cells into osteocytes." (PMID 36415832, 2022). "Moreover, serum BMP2 levels positively correlated with tumor stage and metastatic burden, suggesting that BMP2 might serve as a prognostic marker for survival in NSCLC patients." (PMID 36175474, 2022). "The dosage of BMP-2 and the state of BMSCs in the tumor niche may draw contrasting conclusions." (PMID 34869325, 2021). "Moreover, we noticed that increased concentration of BMP2 within the peripheral blood in mice could lead to the expansion of MDSCs in PB and the infiltration of MDSCs into tumor tissues." (PMID 32195173, 2020). "Thus, BMP2 properly enhanced the expansion of MDSCs to promote tumor growth." (PMID 32195173, 2020).
tumor (continued). "However, further validation is required to establish whether the upregulation of FGF2 and Runx2 is linked to BMP2 expression in EBV-associated NPC and other virus-associated tumours." (PMID 32708289, 2020). "In addition, Lao and investigators demonstrated that BMP-2 could stimulate PCa cell proliferation, tumour growth, and bone metastasis in an animal model." (PMID 30013089, 2018). "Moreover, BMP-2 is considered a putative tumour-suppressor gene in several cancer types." (PMID 30013089, 2018). "FST may have a tumour-suppressor role via the inhibition of BMP2 activity." (PMID 28878391, 2017). "Furthermore, we provide evidence suggesting that targeting BMP2 signalling could be a possible approach to limit CRC tumour growth." (PMID 27708551, 2016). "Additionally, BMP2 inhibited CRC tumor formation in SCID mice." (PMID 27708551, 2016). "Additionally, the effect of BMP-2 on tumor microvessel density (MVD) was examined in vivo." (PMID 27886213, 2016). "Therefore, it is possible that BMP2 is also required by Dragon to induce tumor growth in vivo." (PMID 26029998, 2015). "Thus, BMP-2 has a strong tumor suppressive potential in human RCC and may be useful for predicting OS following radical nephrectomy." (PMID 25797254, 2015). "Indeed, SDF-1 secretion by bone morphogenetic protein-2 increased tubular formation of microvascular endothelial cells and recruiting endothelial progenitor cells, and stimulated tumour growth directly, acting through CXCR4, which is expressed by carcinoma cells." (PMID 19773759, 2009). "We have recently shown that BMP2 in vitro treatment, known to promote glial differentiation in GBM derived cells, resulted to be less effective under hypoxia, suggesting that hypoxia and also HIF-1α may preserve GBM tumour cell stemness by de-sensitizing cells to pro-differentiating BMP2 stimulus." (PMID 19587783, 2009). "This suggests that pro-differentiating agents, such as BMPs, may promote a metabolic shift toward oxidative phosphorylation in tumor cells and that BMP2, by decreasing intracellular succinate through induction of SHD activation, may increase PHD2 activity leading to HIF-1α modulation." (PMID 19587783, 2009). "However, BMP-2 staining positively correlated with tumor grade (r = 0.25, p = 0.02, Spearman test)." (PMID 19366455, 2009). "Specifically, the upregulation of SMAD1, SMAD3, SMAD4, BMP2, MAPK1, and SKIL—driven by promoter hypomethylation and reduced expression of tumor-suppressive microRNAs—leads to enhanced activation of both canonical and non-canonical branches of TGF-β signaling." (PMID 40869118, 2025). "It facilitates the signaling of TGF-β and BMP-2 in chondrogenesis, osteogenesis, tissue fibrosis, vascular and ECM remodeling and tumor development by providing a multimeric environment through which growth factor binding and receptor activation can occur." (PMID 41009743, 2025). "BMP2, BMP4, and BMP7 are canonical growth-inhibitory ligands known to suppress tumor progression by inducing apoptosis and inhibiting EMT in CRC and other cancers." (PMID 40564222, 2025). "The H3K27me3 modification silences tumor suppressor genes, such as CDKN2A, as well as differentiation-related genes, like bone morphogenetic protein 2 (BMP2)." (PMID 40099195, 2025). "A recent study revealed that TANs can secrete bone morphogenetic protein 2 (BMP2) and TGF-β2, triggering the expression of miR-301b-3p in HCC cells within the tumor microenvironment." (PMID 39679376, 2024). "According to their expression in TCGA patients, both unpaired and paired analyses indicated that BMP2 and TWIST1 were highly expressed in tumor samples." (PMID 38610001, 2024). "This decision was based on a study in which BMP-2 significantly promoted OSA cell growth and increased tumor cells’ mobility and invasiveness in vitro." (PMID 39335226, 2024). "Lower expression of BMP2 and BMP6, in the primary tumours, was correlated with poor overall survival (OS) in the RNA sequencing analysis (n=1090)." (PMID 37333824, 2023).
tumor (continued). "Bone morphogenetic protein 2 (BMP2) is highly overexpressed in human non-small cell lung cancer (NSCLC) and correlates with tumor stage and metastatic burden." (PMID 36175474, 2022). "The hASC were distinguished by the lowest BMP-2 and BMP-6 transcript levels compared to the tumour cell lines." (PMID 36139691, 2022). "Elevated expression of BMP-2 is found in HCC and is positively correlated to angiogenesis in tumor tissues." (PMID 35693928, 2022). "It has been well documented that HAMP expression is positively regulated by BMP2/4/6/7 and IL6, while tumor-derived IL6 suppresses TH1 cell functionality." (PMID 36532749, 2022). "To analyse the expression of proteins of interest in the PDX model, we performed IHC staining for BMP2, BMP4, SMAD4 and SHH on tumor, lung and colon tissue 28 days post treatment." (PMID 35902550, 2022). "By co-culture with HCC cells, TANs were found to contribute essentially to tumor cell stemness by secretion of TGF-β2 and bone morphogenetic protein 2 (BMP2) to hyperactivate NF-κB signaling." (PMID 36293184, 2022). "In vitro culture of CSCs with BMP2 mimicked the impact of CA-MSCs on CSCs, while in vivo and in vitro MSC-promoted tumor growth was partly suppressed after the BMP2 signaling pathway was inhibited." (PMID 33472580, 2021). "BMP2 is a member of the TGF-ß superfamily and is involved in cell proliferation and differentiation during tumour formation." (PMID 33461604, 2021). "BMP-2 and TGF-β1 expression was observed in the cytoplasm of the tumor cells, whereas Gli2 and pSmad2/3 expression was observed in the nucleus of the tumor cells." (PMID 33388078, 2021). "The neutrophils secrete several inflammatory, immunoregulatory and angiogenic factors, including NE, PR3, CathG, MMPs, VEGF, Bv8 (prokineticin 2), oncostatin M, IL-1β, TGFβ2, BMP2 and HGF, that modulate the tumor microenvironment and affect tumor growth." (PMID 34572138, 2021). "Among 11 BMPs, BMP3 and BMP8A expression levels were upregulated, and 5 BMPs (BMP2, BMP5, GDF5, BMP6, and GDF10) downregulated in tumor tissues compared with normal tissues." (PMID 34745928, 2021). "It has been reported that MMP1 enhanced tumor cell invasiveness by increasing vascular endothelial growth factor (VEGF) and bone morphogenetic protein 2/4." (PMID 32703314, 2020). "These cells play an initial tumor-suppressor role, but the neoplastic cells can progressively induce the differentiation from NPC to astrocyte via the BMP-2 (bone morphogenetic protein 2) pathway." (PMID 33143050, 2020). "In human cancers, neutrophils exert tumor-promoting functions by producing a variety of factors, including HGF, CCL17, BMP2, among others." (PMID 32903528, 2020). "Increased OCLN and decreased BMP2 expression inhibit the epithelial-mesenchymal transition (EMT), an important stage in tumor cell invasion of tissues." (PMID 28755312, 2017). "The following marker genes were differentially expressed in the triphasic tumours relative to the blastemal tumours: PA (LHX1), RV/CSB/SSB (BMP2, CDH6, JAG1, PAPSS2), ePT and/or imHL (CIDEB, CLIC6, UNC5CL, VDR), and early DT/imHL (KCNJ1)." (PMID 29040332, 2017). "In conclusion, our results suggest that BMP2 overexpression in NPC enhances proliferation, invasion and EMT of tumor cells through the mTORC1 signaling pathway." (PMID 28455969, 2017). "Significant reduction in tumor growth was observed for the LV-BMP2-HCT116 tumours, corroborating the in vitro inhibitory observations of BMP2." (PMID 27708551, 2016). "While our study suggest a suppressive role for BMP2 in CRC, the precise role for the BMP signalling in tumour development is controversial since it has been reported to either promote or inhibit tumorogenesis." (PMID 27708551, 2016). "We employed HCT116 as a cell model for CRC; overexpression of BMP2 inhibited CRC proliferation, migration, colony and spheroid formation and in vivo tumor growth, demonstrating a tumor suppressive role for BMP2." (PMID 27708551, 2016).
tumor (continued). "We employed lentiviral gene transfer technology to overexpress BMP2 in the human HCT116 CRC cell line, and examined its effects on cell proliferation, migration, clonogenic potential, drug resistance, and in vivo tumour growth." (PMID 27708551, 2016). "Our in vitro data further reveals that GC cell lines over-expression Aplein and its receptor APJ, together with the other cytokines which are known to facilitate tumor metastasis and progression, including IL-1, IL6, MMP1, MMP9 and BMP-2." (PMID 27733135, 2016). "Evidence suggests that BMPs, in particular BMP2, is highly expressed in NSCLC and promotes tumor growth, invasion, and metastasis." (PMID 26701726, 2016). "In the current study, we have demonstrated that enhanced expression of BMP2 in CRC cells reduced their growth, enhanced apoptosis and decreased tumor development in vivo." (PMID 27708551, 2016). "This situation is reminiscent of what has been reported about activation of BMP2- and BMP4-dependent pathways in other tumor types." (PMID 26337467, 2015). "Further, there was also a decrease in bone morphogenetic protein 2 (BMP2), cMyc, and ALDH levels while Klotho, a tumor suppressor, was up-egulated with retinal treatment." (PMID 26819566, 2015). "BMP-2 methylation status, BMP-2 mRNA expression, tumor stage, and tumor grade were identified as significant factors contributing to OS in univariate analysis." (PMID 25797254, 2015). "In vitro treatment with BMP2 mirrored the effects of CA-MSCs on cancer stem cells while inhibiting BMP signaling, whereas, in vivo, BMP2 partially inhibited MSC-promoted tumor growth." (PMID 26694366, 2015). "These immunohistochemical data suggest that tumor cells expressing BMP5 and BMP6 induce the transformation of mesenchymal cells, which normally express BMP2 and BMP4, in preosteoblasts and osteoblasts." (PMID 25529855, 2014). "In a follow-up study, pre-treatment of ALDHBr cells with bone morphogenetic protein-2 (BMP-2), which belong to a class of molecules known to be important in bone and cartilage formation, can effectively inhibit the tumor-initiating properties of ALDHBr cells." (PMID 23819111, 2013). "When BMP-2 action is down-regulated by treatment with the BMP antagonist, noggin, PC3 cells have less migration and invasion in vitro and less tumor formation in vivo." (PMID 23977121, 2013). "We also found differences in high oxygen and BMP2 sensitivity between GBM cells and normal cells that should be further investigated to better define tumor cell biology." (PMID 19587783, 2009). "Conversely, in normal SVZ cells BMP2 was operating in an opposite way, promoting a nearly 10% increase of HIF-1α activity, pointing to differences between normal and tumor cells in BMP2 responsiveness." (PMID 19587783, 2009). "The tumor formed by CMT U309, clone 6, i.e. a clone highly expressing BMP-4 in vitro, was strongly positive for BMP-2/4." (PMID 19771160, 2009). "Despite a physiologic tumour samples variability, we recorded a 40% reduction of HIF-1α transcriptional activity under hypoxia following 8 hr of BMP2 treatment compared to untreated cells." (PMID 19587783, 2009). "In this study, as a SMG based on WES data analysis, two novel in-frame deletions of BMP2 (p.Val381del and p.Leu382_Tyr385del) were identified in the tumor sample of case 1, which have not been reported previously." (PMID 40936753, 2025). "The immunohistochemical analysis revealed that the tumor expressed OST and BMP-2 (bone morphogenetic protein-2), which may be responsible for the process of ossification." (PMID 37510722, 2023). "BMP2 expression in salivary glands has been found to be predominantly tumor-induced, and no study to date has examined BMP2 expression after duct ligation in salivary glands." (PMID 37033127, 2023). "In addition to these, BMP2, BMP6 and GDF5 were highly expressed in the TNBC tumours compared with tumours of other subtypes." (PMID 37333824, 2023).